CYP39A1 (cytochrome P450 family 39 subfamily A member 1)
Description:
A cytochrome P450 monooxygenase involved in neural cholesterol clearance through bile acid synthesis. Catalyzes 7-alpha hydroxylation of (24S)- hydroxycholesterol, a neural oxysterol that is metabolized to bile acids in the liver. Mechanistically, uses molecular oxygen inserting one oxygen atom into a substrate, and reducing the second into a water molecule, with two electrons provided by NADPH via cytochrome P450 reductase (CPR; NADPH-ferrihemoprotein reductase).
Tractability: Antibody: UniProt predicts a signal peptide or a membrane-spanning region. PROTAC: ubiquitination databases record sites on it; its protein half-life has been measured.
Gene: Protein-coding gene on chromosome 6 (46,549,383 to 46,652,830, reverse strand). Ensembl gene ENSG00000146233.
Subcellular location: Endoplasmic reticulum membrane; Microsome membrane
Pathways (Reactome):
Metabolism: Endogenous sterols; Synthesis of bile acids and bile salts via 24-hydroxycholesterol
Gene Ontology:
Molecular function: 24S-hydroxycholesterol 7-alpha-hydroxylase activity; protein binding; oxysterol 7-alpha-hydroxylase activity; steroid hydroxylase activity; heme binding; iron ion binding; monooxygenase activity; oxidoreductase activity, acting on paired donors, with incorporation or reduction of molecular oxygen; steroid 7-alpha-hydroxylase activity
Biological process: bile acid biosynthetic process; cholesterol homeostasis; digestion; sterol metabolic process; cholesterol catabolic process
Cellular component: endoplasmic reticulum membrane; intracellular membrane-bounded organelle
Genetic constraint (gnomAD): Loss-of-function variants: 25 observed, 31.93 expected, observed/expected ratio (o/e) 0.78, 90% interval 0.57 to 1.09. The upper end of that interval is the gene's LOEUF score, 1.09, which puts it in group 4 of 6, group 1 being the genes least tolerant of losing a copy. Missense variants: 369 observed, 395.56 expected, observed/expected ratio (o/e) 0.93, 90% interval 0.86 to 1.02. Synonymous variants: 157 observed, 142.21 expected, observed/expected ratio (o/e) 1.1, 90% interval 0.97 to 1.26.
Homologues: Orthologues: chimpanzee CYP39A1 (90% identical), dog CYP39A1 (85% identical), pig CYP39A1 (81% identical), macaque CYP39A1 (77% identical), mouse Cyp39a1 (75% identical), rat Cyp39a1 (73% identical), rabbit CYP39A1 (72% identical), tropical clawed frog cyp39a1 (51% identical), zebrafish cyp39a1 (49% identical). Paralogues in human: CYP7B1 (26% identical), CYP7A1 (25% identical).
Diseases named in the same sentence as CYP39A1 in open-access papers:
CYP39A1 is named in the same sentence as 29 diseases in open-access papers, as found by Europe PMC text mining. Sharing a sentence is not in itself a finding about the gene and the disease. The quoted sentences say what the papers report.
hepatocellular carcinoma (5 papers, 2020 to 2025). A malignant tumor that arises from hepatocytes. "Cyp39a1, typically recognized as a specific marker of hepatocellular carcinoma, was also found to be downregulated in AP." (PMID 41007695, 2025). "Investigating the expression of the CYP39A1 gene, it was described that the nuclear receptor RORα regulates CYP39A1 expression levels in human hepatoma cells." (PMID 39403150, 2024). "CYP39A1 was upregulated by RORα overexpression in HEK293 cells, while RORα knockdown by siRNA significantly downregulated CYP39A1 expression in human hepatoma cells." (PMID 32392803, 2020). "We showed, for the first time, that the nuclear receptor RORα regulates CYP39A1 expression levels in human hepatoma cells, which can be induced by SR1078, a RORα agonist." (PMID 32392803, 2020). "Moreover, CYP39A1 was upregulated through RORα overexpression in HEK293 cells, while RORα knockdown by siRNA significantly downregulated CYP39A1 expression in human hepatoma cells, suggesting that CYP39A1 expression is activated via RORα nuclear receptors." (PMID 32392803, 2020). "Moreover, clinical studies showed that patients with hepatocellular carcinomas (HCC) had lower liver Cyp39a1 expression." (PMID 36012616, 2022). "Our results indicated that CYP39A1 was mainly expressed in the cytoplasm of hepatocellular carcinoma cells or hepatocytes rather than in stromal cells." (PMID 35003516, 2021). "However, the role of CYP39A1 in hepatocellular carcinoma (HCC) has not yet been clarified." (PMID 35003516, 2021).
Alzheimer disease (3 papers, 2020 to 2023). A progressive, neurodegenerative disease characterized by loss of function and death of nerve cells in several areas of the brain leading to loss of cognitive function such as memory and language. "Increasing the expression of the CYP39A1 protein has the potential to suppress 24S-hydroxycholesterol aggregation in the brain and act as a therapeutic target for neurodegenerative diseases involving abnormal amyloid-β accumulation such as Alzheimer’s disease." (PMID 35431771, 2022). "Interestingly, the gene correlated with taurine, CYP39A1 is directly involved in the neural cholesterol clearance pathway of bile acids as identified in PM brain tissues of Alzheimer’s disease cohorts." (PMID 35431771, 2022). "In addition, 24S-OHC accumulation due to abnormal expression of CYP46A1 and CYP39A1 results in neuronal death, contributing to Alzheimer’s disease (AD)-related neurodegeneration." (PMID 32392803, 2020). "Increasing the expression of CYP39A1 could be beneficial to reduce brain 24S-hydroxycholesterol, whose accumulation has been shown to be related to oxidative stress and reported in the brain of patients with dementia and Alzheimer’s disease." (PMID 37601072, 2023).
glaucoma (3 papers, 2021 to 2025). Increased pressure in the eyeball due to obstruction of the outflow of aqueous humor. "The connection between CTNNB1 and CYP39A1 is particularly intriguing given CTNNB1’s known role in the canonical Wnt signaling pathway—a pathway extensively linked to glaucoma through its regulation of cellular proliferation, differentiation, and survival processes." (PMID 41042282, 2025). "Likewise, CYP39A1 is an enzyme involved in cholesterol and oxysterol metabolism, and its relevance to glaucoma is supported by recent genetic evidence: a rare variant in CYP39A1 has been associated with a higher occurrence of XFG and more severe disease progression." (PMID 41042282, 2025). "Thus, our bioinformatic analysis revealed upregulation of two CYP enzymes, CYP1B1 and CYP39A1, in TM cells model of glaucoma pathogenesis." (PMID 34356513, 2021). "RBMS3 was not highlighted significantly in previous analyses, whereas CYP39A1 exhibited significant correlation with SE, indicating its potential direct relevance in glaucoma." (PMID 41042282, 2025). "Also, the CYP39A1 G204E carriers had almost a tenfold increased risk for glaucoma-related blindness and a shorter time until blindness (13.7 months) as compared to patients with XFS, who did not carry any CYP39A1 mutations (105.9 months)." (PMID 37392222, 2023).
melanoma (3 papers, 2016 to 2021). A malignant, usually aggressive tumor composed of atypical, neoplastic melanocytes. "Currently, CYP39A1 is expressed at lower levels in malignant melanoma and cholangiocarcinoma." (PMID 35003516, 2021). "Moreover, CYP39A1 was expressed at lower levels in malignant melanoma and cholangiocarcinoma." (PMID 35003516, 2021). "Thus, genes controlling the turnover of vitamin D (CYP27B1, CYP24A1), vitamin A (ALDH1A3, AKR1B10), and cholesterol (CYP7B1), were up-regulated in psoriasis, whereas melanomas showed downregulation of genes regulating turnover of vitamin A (AKR1C3), and cholesterol (CYP39A1)." (PMID 26901218, 2016).
cholangiocarcinoma (2 papers, 2021 to 2025). A carcinoma that arises from the intrahepatic biliary tree (intrahepatic cholangiocarcinoma) or from the junction, or adjacent to the junction, of the right and left hepatic ducts (hilar cholangiocarcinoma). "A similar study also showed that CYP39A1 might be a promising protective-prognostic factor and that altered expression of CYP39A1 might play a useful role in cholangiocarcinoma progression." (PMID 35003516, 2021).
neutropenia (2 papers, 2016 to 2022). A decrease in the number of neutrophils found in the blood. "Among other SNPs that are associated with drug-induced neutropenia in the non-US population, only 1 was significant (i.e., CYP39A1)." (PMID 36134663, 2022).
ovarian carcinoma (2 papers, 2014 to 2021). A malignant neoplasm originating from the surface ovarian epithelium. "Furthermore, the promoter of the CYP39A1 gene was hypermethylated in ovarian cancer, resulting in its transcriptional disorder, which caused metabolic disorders of cholesterol and quinoline acid and contributed to the occurrence of ovarian cancer." (PMID 35003516, 2021).
cholestasis (1 paper, 2021). Impairment of the bile flow caused by obstruction within the liver, or outside the liver in the bile duct system. "Moreover, it was found that CYP39A1 mRNA was increased in models of hepatoprotection mice from cholestasis induced by lithocholic acid (LCA), which toward the formation of less toxic bile acids therefore leading less liver injury." (PMID 35003516, 2021).
colorectal cancer (1 paper, 2016). A primary or metastatic malignant neoplasm that affects the colon or rectum. "This study has profiled the expression of the cholesterol metabolising enzymes CYP2R1, CYP7B1, CYP8B1, CYP27A1, CYP39A1, CYP46A1 and CYP51A1 in primary colorectal cancer tissue using a well-characterised cohorts of colorectal cancers." (PMID 27341022, 2016). "Immunohistochemistry was performed on a colorectal cancer tissue microarray containing 650 primary colorectal cancers using monoclonal antibodies to CYP2R1, CYP7B1, CYP8B1, CYP27A1, CYP39A1, CYP46A1 and CYP51A1, which we have developed." (PMID 27341022, 2016). "However, CYP2R1 (p=0.034), CYP8B1 (p=0.002), CYP39A1 (p<0.001), CYP46A1 (p<0.001) and CYP51A1 (p=0.001) each demonstrated significantly reduced expression in paired lymph node metastasis compared to Dukes C (stage 3) colorectal cancer." (PMID 27341022, 2016).
COVID-19 (1 paper, 2021). A disease caused by infection with severe acute respiratory syndrome coronavirus 2. "It was reported that CYP39A1 was significantly downregulated in the blood plasma of severe COVID-19 patients with liver dysfunction." (PMID 35003516, 2021).
lipid metabolism disorders (1 paper, 2025). "In this study, seven core genes (Amacr, Cyp39a1, Echs1, Gpd2, Osbpl9, Acsl4, and Mcee) closely associated with lipid metabolism disorders in AP were systematically identified through the integration of bioinformatics and machine learning approaches." (PMID 41007695, 2025).
liver cancer (1 paper, 2023). An epithelial or non-epithelial malignant neoplasm that arises from the liver. "WD-reduced hepatic Cyp39a1 (cytochrome P450 family 39 subfamily a member 1) and increased Gramd1b (GRAM domain containing 1B) were also changed in human liver cancer and metabolic liver disease, respectively." (PMID 37571345, 2023).
liver dysfunction (1 paper, 2021). "Recent studies also indicated that CYP39A1 was lower expressed in patients with liver dysfunction." (PMID 35003516, 2021).
liver fibrosis (1 paper, 2021). "Another study revealed that higher hepatic mRNA levels of hepatic CYP39A1 were linked to higher serum cholesterol but protect against steatosis, steatohepatitis, and liver fibrosis in a subset of patients." (PMID 35003516, 2021).
Parkinson ́s Disease (1 paper, 2024). "Single nucleotide polymorphisms (SNPs) with statistically significant association (p-value <0.05) to Parkinson ́s Disease (PD) for the genes of the four human cholesterol degrading cytochrome P450, CYP7B1, CYP27A1, CYP39A1 and CYP46A1." (PMID 39403150, 2024).
phaeochromocytoma (1 paper, 2016). "However, some genes associated with steroid, organic hydroxy compound, and alcohol-related processes that were upregulated in ZG samples from phaeochromocytoma patients (eg, CYP11B2, CYP39A1, PLA2G1B, and SULT1E1), were not significantly upregulated in ZG samples from adrenals with an APA." (PMID 27777363, 2016).
tumor (4 papers, 2016 to 2022). "Meanwhile, CYP39A1 encoded a member of the cytochrome P450 superfamily of enzymes and played an important role in tumor progression and neurodegenerative disorder." (PMID 36699448, 2022). "In summary, low expression of CYP39A1 was associated with carcinogenesis, tumor differentiation and progression, and poor overall survival of patients with HCC." (PMID 35003516, 2021). "The downregulation of CYP39A1 is associated with HCC carcinogenesis, tumor differentiation, and poor overall survival." (PMID 36557005, 2022). "The results indicated that CYP39A1 expression was positively correlated with tumor cell differentiation." (PMID 35003516, 2021). "Comparing CYP39A1 negatively staining tumours versus CYP39A1 positively staining tumours, CYP39A1 expression demonstrated a statistically significant relationship with survival (HR=1.468, 95% CI=1.157-1.861, χ2=10.21, p=0.001)." (PMID 27341022, 2016). "Downregulation of CYP39A1 is associated with HCC carcinogenesis, tumor differentiation, and poor overall survival, suggesting that CYP39A1 may serve as a tumor suppressor gene and novel biomarker for HCC patients." (PMID 35003516, 2021). "Furthermore, we found that CYP39A1 was decreased in the tumor cells of Akt/c-Met-induced HCC mouse model (P < 0.001), however, it was increased in the oral administration of osthole group, especially in the high dose of osthole group." (PMID 35003516, 2021). "Furthermore, bioinformatic analysis also indicated that CYP39A1 mRNA expression was correlated with tumor grade (cell differentiation)." (PMID 35003516, 2021). "CYP39A1 and CYP46A1 were also significantly associated with tumour stage and lymph node stage." (PMID 27341022, 2016). "Therefore, combining the results from cell viability data in vitro, CYP39A1 might serve as a tumor suppressor gene in HCC." (PMID 35003516, 2021). "CYP7B1, CYP8B1, CYP39A1, CYP46A1 and CYP51A1 each displayed a statistically significant relationship with location of tumour in the colon versus the rectum." (PMID 27341022, 2016). "When the primary tumours of lymph node positive cases (Dukes C, stage 3) were compared to the paired lymph node metastasis, expression of CYP2R1, CYP8B1, CYP39A1, CYP46A1 and CYP51A1 were each significantly reduced in the lymph node metastasis." (PMID 27341022, 2016). "The remaining target proteins had very low frequencies of strong immunostaining and no tumour showed strong CYP39A1 immunoreactivity." (PMID 27341022, 2016). "The mean survival for CYP39A1 negative/weak staining tumours (n=617) was 117 months (95% CI 109-126), declining to 33 months (95% CI 17-50) for patients whose tumours demonstrated moderate immunostaining for CYP39A1 (n=12)." (PMID 27341022, 2016). "However, CYP39A1 expression was not correlated with sex, age, tumor size, nodal metastasis, distant metastasis, or TNM stage (P > 0.05)." (PMID 35003516, 2021).
neurodegenerative disease (3 papers, 2020 to 2023). A disorder of the central nervous system characterized by gradual and progressive loss of neural tissue and neurologic function. "The abnormal lower expression of CYP39A1 gene results in buildup of 24S-hydroxycholesterol inducing amyloid-β peptide accumulation in neurodegenerative disease." (PMID 35431771, 2022). "Aberrant CYP39A1 expression may contribute to neurodegenerative diseases like Alzheimer’s, however, its role in NOWS is not yet known." (PMID 38264209, 2023). "Abnormal CYP39A1 expression results in accumulation of 24S-OHC, influencing neurodegenerative disease-related deterioration; thus, it is important to understand the normal elimination of 24S-OHC and the system regulating CYP39A1, a selective hepatic metabolic enzyme of 24S-OHC." (PMID 32392803, 2020).
cancer (2 papers, 2021 to 2022). A tumor composed of atypical neoplastic, often pleomorphic cells that invade other tissues. "Similarly, it was also found that CYP39A1 mRNA expression in the cancer tissues (7.14%, 1/14) was lower than that in matched adjacent noncancerous tissues (78.57%, 11/14) (P < 0.01, paired t-test)." (PMID 35003516, 2021). "CYP450 plays crucial roles in these intertwined mechanisms of cholesterol homeostasis, such as CYP7A1, 27A1, 46A1, CYP8B1, and CYP39A1, which are cholesterol oxidation products whose expression may be dysregulated in inflammation-related diseases, including cancer." (PMID 35003516, 2021).
CYP39A1 also shares sentences with these, for which no sentence is quoted: metabolic disorders (2 papers); Blindness (1); breast carcinoma (1); dementia (1); gallbladder cancer (1); lymph node metastasis (1); nodular goiter (1); psoriasis (1); steatosis (1); thyroid cancer (1).